STAT3 (signal transducer and activator of transcription 3)
Diseases named in the same sentence as STAT3 in open-access papers (continued):
Sharing a sentence is not in itself a finding about the gene and the disease.
tumor (continued). "We observed a parallel increase in STAT3 and IL-6R in HCV-infected HCC as compared with control liver, suggesting coordinate regulation of inflammatory response molecules in tumor development." (PMID 26217396, 2015). "A recent study showed that STAT3 and HIF-1α form transcription factor complexes that drive target gene expression, providing a direct cooperative link between STAT3 and HIF-1α in tumor progression." (PMID 26343197, 2015). "We observed phosphorylation of STAT3 (Tyr 705) and STAT5 (Tyr694) in pancreatic tissue of KPC and KPC-Brca1 that localized to both the tumor and stromal cells." (PMID 26575024, 2015). "As a transcription factor, STAT3 regulates Mcl1, Survivin, p21, Bcl-xl, Bcl-2, c-Myc, Cyclin D1, and VEGF expression and therefore correlates with tumorigenesis and tumor progression." (PMID 26166037, 2015). "In contrast, these independent changes in Stat3 and HIF-1α induced by tanshinone-1 synergistically inhibit the tube formation of endothelial cells and the VEGF secretion from tumor cells." (PMID 26202747, 2015). "Consistent with Grandis and colleagues, the present study also demonstrated that blockade of STAT3 can significantly induced cell death in HNSCC cell lines and obviously decreased tumor volumes in xenograft mice model." (PMID 26556875, 2015). "The multiple effectors of Src include the PI3K/Akt, Ras/Raf/MAPK, STAT3/STAT5B, and p130 pathways; moreover, VEGFR promotes migration of tumor cells through a Src-dependent pathway." (PMID 26504896, 2015). "Here we report that the PI3K/Akt1/IL-6/STAT3 signalling pathway regulates generation and stem cell-like properties of Non-Small Cell Lung Cancer (NSCLC) tumor initiating cells (TICs)." (PMID 26486080, 2015). "STAT factors can either inhibit (mostly STAT1) or support (mostly STAT3 and STAT5) tumour cell proliferation." (PMID 25880691, 2015). "The activities of the transcription factors Twist1/2, SNAI1/2, AP1, NF-κB, and Stat3 were suppressed by doxycycline, which reversed EMT and inhibited signal transduction, thereby suppressing tumor growth and metastasis." (PMID 26512779, 2015). "STAT3 is a well-known inducer of MMPs and angiogenic factors including TGF-β, CD31, COX-2 and Ang2 in tumor cells." (PMID 26575424, 2015). "Abnormal signaling pathway activation, including AKT, IL-6/STAT3 and MAPK/ERK, is considered to be significant for the EMT, pro-tumorigenic inflammatory cytokine secretion, invasion and metastasis of tumor cells." (PMID 25788270, 2015). "Specifically, activated STAT3 increases the invasive abilities of BrC cells by initiating the transcription of the MMP2 and MMP9 genes, whereas blocking STAT3 activity suppresses MMP2 and MMP9 expression, tumor invasion, and lung metastasis." (PMID 26360780, 2015). "We have shown that endothelial cells secrete IL-6, CXCL8, and EGF that induce phosphorylation of STAT3, AKT, and ERK in tumor cells, and that these phosphorylation events enhance tumor cell survival and migration." (PMID 26287605, 2015). "As such, the purpose of this study was to characterize activation and expression of phosphorylated STAT3 (pSTAT3) in feline OSCC cell lines and tumor samples and to investigate the biologic activity of LLL12 in feline OSCC cell lines." (PMID 26272737, 2015). "We suggest that BSN inhibits STAT3 signaling through modulation of PIAS-3 and SOCS-3, thereby attenuating tumor growth and increasing sensitivity to paclitaxel." (PMID 25788267, 2015). "Both STAT3 and STAT5 increase tumor cell proliferation, survival and invasion, while suppressing anti-tumor immunity." (PMID 26397137, 2015). "Then, we extended the time course experiments to 24 hours, and observed the same relationship between STAT3, Akt, and ERK phosphorylation in tumor cells induced by endothelial cell-secreted factors." (PMID 24533454, 2014).
tumor (continued). "Recent findings showed that sorafenib inhibited tumor growth through Raf-MEK-MAPK-independent pathways and STAT3 was a major kinase-independent target of sorafenib in HCC, and sorafenib inhibited growth and metastasis of HCC by blocking STAT3." (PMID 24418169, 2014). "Given this new finding, two mechanisms can be targeted to reduce tumor growth by ETBF: one, gut microbes can be therapeutically targeted with antibiotics and two, the long-term activation of Stat3 can be inhibited to decrease a Th17 immune response." (PMID 24987392, 2014). "Inhibition of the HIF-1α/STAT3/VEGF pathway using multiple plant derived agents and siRNA, have shown reduction of PCa tumor cell growth both in vitro and in vivo." (PMID 24722453, 2014). "STAT3 activity increases production of vascular endothelial growth factor (VEGF) and IL-6, ultimately promoting tumor formation in vivo." (PMID 25505736, 2014). "Finally, STAT3 regulation of genes that may play dual roles in tumor growth will be examined." (PMID 24743777, 2014). "In contrast, in PTEN-proficient mouse astrocytes, STAT3 appeared to behave as a tumor suppressor while simultaneous suppression of PTEN and STAT3 led to astrocyte malignant transformation." (PMID 24743777, 2014). "VEGF is the predominant factor that acts directly to stimulate tumor angiogenesis, and the persistent activation of STAT-3 induces VEGF expression, resulting in tumor angiogenesis." (PMID 25009646, 2014). "Endogenously, the HIC1 (Hypermethylated in cancer 1) gene, a tumor suppressor, forms complex with STAT3 protein through direct interaction between the C-terminal domain of HIC1 and the DNA binding domain of STAT3." (PMID 24743778, 2014). "A firm connection between STAT3 activity and IDO expression has been established in mouse DC, indicating similar patterns of transcriptional regulation of IDO in tumor cells and myeloid cells." (PMID 24657910, 2014). "Given STAT3’s established role in GBM tumorigenesis and tumor suppression, it is a reasonable candidate as a prognostic marker." (PMID 24518612, 2014). "We observed that phosphorylation levels of STAT3, Akt, and ERK were higher in tumor cells exposed to HDMEC CM than in tumor cells exposed to HeLa CM, or unconditioned medium (EBM)." (PMID 24533454, 2014). "Our findings further build on these models by suggesting a role for ezrin in the regulation of IL-6 expression and Stat3 activation leading to the upregulation of VEGF-A/-C and tumour angio/lymphangiogenesis." (PMID 25231728, 2014). "At initiation, STAT3 and STAT5 are generally considered to be oncogenic while STAT1 is considered to have a tumor suppressor role." (PMID 24728078, 2014). "Signal transducer and activator of transcription-3 (STAT3) has been identified as a key regulator of macrophage functions and is involved in several programmes related to tumour progression." (PMID 24708807, 2014). "We observed that phosphorylation levels of STAT3, Akt, and ERK were higher when both tumor cells and keratinocytes were exposed to HDMEC CM than to EBM." (PMID 24533454, 2014). "Similar changes are seen in the JAK/STAT pathway with the activating phosphorylation of the key transcription factor STAT3 being reported in 50%–100% of HCC tumours and rarely in surrounding non-tumour tissue." (PMID 24871369, 2014). "In turn, Let-7 miRNAs have been reported to play role as tumor suppressor, mainly by repression of oncogenes and key regulators of various mitogenic pathways, such as Myc, Hmga2, Ras, JAK and STAT3." (PMID 24498170, 2014). "Activation of IKKβ and STAT3 are activated in CRPC and that this signaling is required for the CXCL13 mediated recruitment of immunosuppressive B cells to the tumor microenvironment." (PMID 24722453, 2014). "Synthetic lethal screening of an EGFR-centered signaling network using a siRNA library revealed that STAT3 is one of the targets that synergize with EGFR antagonists to reduce cancer cell viability and tumor size." (PMID 24662938, 2014).
tumor (continued). "We observed that blockade of endothelial cell-derived IL-6 inhibited STAT3 phosphorylation in cancer cells and expression of CXCL8 (IL-8), a potent pro-angiogenic factor that is strongly correlated with tumor microvessel density." (PMID 24533454, 2014). "In the meantime, interfering with this axis utilizing the NF-κB inhibitor, the IL-6 receptor antibody, the Stat3 inhibitor or down-regulating the expression of Twist reduces the CSC population and results in inhibition of tumor growth and metastasis." (PMID 25038821, 2014). "Signal transducer and activator of transcription 3 (STAT3) is a potent regulator of gliomagenesis through its induction of angiogenesis, host immunosuppression, and tumor invasion." (PMID 24518612, 2014). "In tumor cells, there is continuous STAT-3 activation, resulting in disordered janus tyrosine kinase (JAK)-STAT signal transduction, which is typical of tumor cells during invasion and metastasis." (PMID 25009646, 2014). "The prognostic value of EGFR and its downstream signaling molecules such as STAT3 and ERK1 have been studied in many tumor types." (PMID 25146150, 2014). "However, as this article series is making clear, STAT3 also has several tumor suppressive functions as a transcription factor including regulating genes for other tumor suppressing transcription factors and genes that suppress cell proliferation and survival as well as tumor metastasis." (PMID 24743777, 2014). "Bypassing the growth suppressive signaling leaves gp130-activated signals (STAT3, MAPK, and PI3K/AKT) intact to now serve as downstream effectors to drive aggressive OSM-mediated tumor phenotypes." (PMID 24675570, 2014). "Targeting STAT3 with a small molecule inhibitor blocks hypoxia inducible factor-1 and VEGF expression in vitro and inhibits tumor growth and angiogenesis in vivo." (PMID 24520293, 2014). "More interesting finding is genetic background-independent stimulation of c-Jun expression together with STAT3 and PERK activation promoting cancer cell proliferation and tumour growth." (PMID 24594856, 2014). "Here, we demonstrated that tumor cells exposed to endothelial cell conditioned medium showed significantly higher levels of STAT3, Akt, and ERK phosphorylation than tumor cells exposed to conditioned medium collected from tumor cells." (PMID 24533454, 2014). "Mechanistic studies have revealed that STAT3 directly binds to the promoter region of the VEGF gene and promotes its transcription, thereby enhancing tumor growth and metastasis." (PMID 24995504, 2014). "In this study, we found that SH003 strongly suppressed tumor growth and metastasis of MDA-MB-231 cells defined as TNBC by inhibiting STAT3 activity." (PMID 24976685, 2014). "To gain further insight into the molecular mechanism of the inhibitory effects of YLT192 on tumor cells we evaluated the expression of p44/42 MAPK, STAT3, AKT, and mammalian target of rapamycin (mTOR) in U251 and HCT116 cells 48 h after treatment." (PMID 25112436, 2014). "We observed that when tumor cells were exposed to rhIL-6, the phosphorylation of STAT3, Akt, and ERK followed similar patterns as when tumor cells were exposed to HDMEC CM." (PMID 24533454, 2014). "NF-κB, STAT3, AP-1, CREB and nuclear factor erythroid 2-related factor (Nrf2) are transcription factors that regulate tumor cell proliferation, transformation, survival, invasion, angiogenesis, metastasis, chemoresistance and radioresistance." (PMID 24223660, 2013). "Tumor-primed PBMC and MΦ secrete one specific EGFR agonist, respectively, in combination with OSM, the relevant STAT3 activator." (PMID 23597096, 2013). "Following exposure of primary human monocytes and macrophages to supernatants of a variety of tumor cell lines, we have analyzed transcript and secreted protein levels of EGFR family ligands and of STAT3 activators." (PMID 23597096, 2013).
tumor (continued). "IL-6/STAT3 signaling was reported to stimulating tumor invasion, EMT changes, and promote the surviving tumor cells after therapy to acquire treatment resistance via microenvironment- mediated resistance." (PMID 23806095, 2013). "The HCMV protein US28 is a constitutively active chemokine receptor homologue that induces COX-2 expression and results in STAT3 phosphorylation, which increases the production of VEGF and IL-6 and consequently induce tumor formation in vivo." (PMID 23451089, 2013). "Among seven mammalian STAT proteins, persistent activation of STAT3 followed by STAT5 is frequently detected in majority of human cancer cell lines and tumor tissues." (PMID 24199193, 2013). "In the present study, we sought to further understand the difference in STAT3 function between these two subtypes through mapping its binding regions (BRs) and analyzing gene expression in GCB and ABC patient tumor-derived cell lines." (PMID 24142927, 2013). "Studies have shown tumor escape mechanisms in STAT-1−/− mice, and STAT-3 signaling was identified in the inhibitory effects of IL-10 on DC maturation and migration, and impairment of CD4+ T-cell function." (PMID 24216992, 2013). "Studies have suggested that following STAT3 inhibition, the levels of TNF-α increase, promoting a more inflammatory macrophage/microglia resulting in inhibition of tumor growth." (PMID 24244348, 2013). "In contrast to the tumor suppressor function of activated STAT1, STAT3 is mainly identified as an oncogene." (PMID 23825585, 2013). "Within the tumor microenvironment, IL-6 binds to gp80/gp130, leading to Janus kinase (JAK) activation and phosphorylation of Stat3, which regulates the expression of genes that mediate cellular proliferation and prevent apoptosis." (PMID 24062985, 2013). "Therapies such as monoclonal antibodies and tyrosine kinase inhibitors targeting EGFR have demonstrated limited anti-tumor efficacy; however, reports of combined targeting of EGFR and STAT3 are few." (PMID 24499623, 2013). "We identify HB-EGF and OSM as the key EGFR and STAT3 activators secreted by tumor-primed MΦ, and EREG and OSM as the key activating factors secreted by tumor-primed PBMC." (PMID 23597096, 2013). "For this, we analyzed the untreated and treated tumor tissues to check the activation status of EGFR and its pathway members, AKT, STAT3 and ERK1/2, as well as the mitochondrial caspase-cascade." (PMID 23555785, 2013). "In order to reverse immunosuppression in tumor-bearing hosts, we have evaluated signal inhibition at upstream molecules, such as BRAF-MAPK, STAT3, and Wnt/β-catenin." (PMID 23755373, 2013). "IL6, a direct regulator of breast CSC self-renewal activates STAT3 and NF-κB which secretes additional IL6 and IL8, generating a positive feedback loop between inflammatory cell and tumor cells." (PMID 23799116, 2013). "In other regional inflammation-induced lung spontaneous tumor mouse models, overexpression of MMP12 and Api6 in alveolar type II epithelial cells results in Stat3 activation (increased phosphorylation at Y705) in lung epithelial cells." (PMID 23613996, 2013). "Another STAT3 target gene is the proangiogenic vascular endothelial growth factor (VEGF), involved in tumor invasion and spreading, which directly regulates several matrix metalloproteinases enzymes implicated in tumor cell invasion." (PMID 23738079, 2013). "There are ample evidences supporting a functional role of STAT3 in tumorigensis and progression of NPC through promotion of tumor initiation, growth and invasive properties of cancer cells." (PMID 24380387, 2013). "Previous reports have shown that TAMs contribute to tumor progression through secretion EGF and upregulation of the EGFR/Stat3/Sox-2 signaling pathway." (PMID 24312366, 2013). "We show that the pharmacologic targeting of STAT3 is able to suppress ALDH+ and ALDH+/CD44+/CD24− cells in vitro and in mouse tumor models." (PMID 24376586, 2013).
tumor (continued). "Tumor-primed primary PBMC and MΦ secrete oncostatin-M, and only OSM activates STAT3 in our reporter system." (PMID 23597096, 2013). "STAT3, NF-κB, and HIF-1 signaling contribute to the crosstalk between the tumor and the tumor microenvironment (TME)." (PMID 23094050, 2012). "Consistent with our in vitro results, western blot of the tumor lysate shows that PEITC treatment substantially downregulated HER2 expression and phosphorylation of STAT3." (PMID 22824293, 2012). "A variety of stimuli within the tumor microenvironment can activate kinases like AKT, ERK1/2 and STAT3, including hypoxia." (PMID 23046567, 2012). "Next, we examined EGFR expression in the tumor cells and the effect of erlotinib on the phosphorylation of EGFR, as well as its major downstream signal molecules such as Akt, ERK, Stat3, by Western blotting." (PMID 22209766, 2012). "These two pathways activate transcription factors such as nuclear factor-kappaB (NF-κB), signal transducer and activator of transcription 3 (STAT-3), and hypoxia-inducible factor 1alpha (HIF-1 alpha), in tumor cells." (PMID 22829853, 2012). "Previous studies suggested that MFG-E8 activates diverse array of oncogenic signals such as Stat3, Hedgehog, Akt/PI3K and twist-1, in tumor cells." (PMID 22761839, 2012). "Persistently activated STAT3 and to some extent STAT5, increase tumor cell proliferation, survival and invasion while suppressing anti-tumour immunity." (PMID 23251519, 2012). "Constitutive activation of STAT3 induced by Src and JAK tyrosine kinases participates in growth regulation of tumor cells." (PMID 23166634, 2012). "Given that the tumor-infiltrating immune cells constitute a small minority of the overall tumor population, a limitation of the current study is that this influential subset may have not been fully taken into account in the context of the overall p-STAT3 expression." (PMID 22488042, 2012). "To address the importance of JAK2/STAT3 signaling in human tumor tissue samples, we performed immunohistochemistry (IHC) for JAK2, STAT3 and pSTAT3Y705 on a clinically annotated tissue microarray containing 245 stage I/II NSCLC samples." (PMID 22319590, 2012). "In other tumor models, EGF was shown to trigger an EMT with up-regulation of either SNAI1 or TWIST1 possibly through STAT3 activation." (PMID 22272264, 2012). "Thus, we hypothesized that higher systemic (non-CNS distant metastasis) tumor levels of p-STAT3 would predispose patients to the development of CNS metastasis and would be a negative prognostic factor for survival." (PMID 22488042, 2012). "It is thus likely that inhibition of STAT3 signaling by LLL12 inhibits tumor growth through a combination of its direct and indirect effects on angiogenesis and direct inhibitory effect on tumor cell proliferation." (PMID 22530037, 2012). "Recently, Niu and colleagues reported that constitutive activity of STAT3 up-regulated VEGF expression and tumor angiogenesis." (PMID 22260501, 2012). "Thus, the combination of AZD1480 with cediranib markedly reduced tumor volume, and microvascular density, indicating that up regulation of the STAT3 pathway can mediate resistance to antiangiogenic therapy and combinational approaches may delay or overcome resistance." (PMID 23013619, 2012). "Antisense STAT3 oligonucleotide or STAT3 inhibitors, other than LLL12, have been shown to reduce microvessel density in tumor models." (PMID 22530037, 2012). "Despite the promising in vitro results of STAT3-inhibition with AG490 or related molecules, these compounds exerted only limited efficacy in tumor models in vivo." (PMID 22418922, 2012). "Wei and colleagues also reported that overexpression of constitutively activated mutant STAT3 sufficiently increased VEGF expression and tumor angiogenesis in vivo." (PMID 22260501, 2012). "Numerous studies have shown that expression of PTEN, STAT3 and VEGF-C, which can regulate tumor cell growth, is closely related during tumor development." (PMID 23170117, 2012).